AIG1 (androgen induced 1)
Description:
Hydrolyzes bioactive fatty-acid esters of hydroxy-fatty acids (FAHFAs), but not other major classes of lipids. Show a preference for FAHFAs with branching distal from the carboxylate head group of the lipids.
Synonyms: AIG-1; dJ95L4.1; FLJ10485
Tractability: Antibody: UniProt places it where antibodies can reach, with high confidence; UniProt predicts a signal peptide or a membrane-spanning region; its Gene Ontology location is reachable by antibodies, with medium confidence. PROTAC: its protein half-life has been measured.
Gene: Protein-coding gene on chromosome 6 (143,060,496 to 143,341,058, forward strand). Ensembl gene ENSG00000146416.
Subcellular location: Cell membrane
Subcellular location (Human Protein Atlas): Golgi apparatus
Gene Ontology:
Molecular function: protein binding; hydrolase activity
Biological process: long-chain fatty acid catabolic process
Cellular component: membrane; plasma membrane
Genetic constraint (gnomAD): Loss-of-function variants: 20 observed, 22.73 expected, observed/expected ratio (o/e) 0.88, 90% interval 0.62 to 1.28. The upper end of that interval is the gene's LOEUF score, 1.28, which puts it in group 5 of 6, group 1 being the genes least tolerant of losing a copy. Missense variants: 256 observed, 259.38 expected, observed/expected ratio (o/e) 0.99, 90% interval 0.89 to 1.1. Synonymous variants: 94 observed, 95.96 expected, observed/expected ratio (o/e) 0.98, 90% interval 0.83 to 1.16.
Homologues: Orthologues: pig AIG1 (97% identical), rabbit AIG1 (97% identical), macaque AIG1 (97% identical), chimpanzee AIG1 (95% identical), mouse Aig1 (95% identical), rat Aig1 (89% identical), guinea pig AIG1 (79% identical), zebrafish aig1 (72% identical), Drosophila melanogaster CG3625 (34% identical), Drosophila melanogaster CG11601 (31% identical), Drosophila melanogaster CG6149 (31% identical), dog AIG1 (23% identical), and 4 more. Paralogues in human: ADTRP (33% identical).
Diseases named in the same sentence as AIG1 in open-access papers:
AIG1 is named in the same sentence as 23 diseases in open-access papers, as found by Europe PMC text mining. Sharing a sentence is not in itself a finding about the gene and the disease. The quoted sentences say what the papers report.
acute lymphoblastic leukemia (1 paper, 2022). Leukemia with an acute onset, characterized by the presence of lymphoblasts in the bone marrow and the peripheral blood. "Previous studies have determined AIG1 may serve as a new biomarker for the diagnosis and prognostic evaluation of HCC and is associated with the thiopurine treatment of acute lymphoblastic leukemia." (PMID 35923577, 2022).
amoebic colitis (1 paper, 2010). "Additionally, the expression of aig1 genes was highly regulated in HM-1:IMSS trophozoites, obtained from a murine model of amoebic colitis." (PMID 20102605, 2010).
glioma (1 paper, 2020). A benign or malignant brain and spinal cord tumor that arises from glial cells (astrocytes, oligodendrocytes, ependymal cells). "Within the Hippo pathway, we here demonstrate, in human gliomas, a functional interaction of a transmembrane protein, prostate transmembrane protein, androgen induced 1 (PMEPA1) with large tumor suppressor kinase 1 (LATS1)." (PMID 31605013, 2020).
hepatocellular carcinoma (1 paper, 2025). A malignant tumor that arises from hepatocytes.
Insulin resistance (1 paper, 2024). Increased resistance towards insulin, that is, diminished effectiveness of insulin in reducing blood glucose levels. "Adipocyte-specific knockout of IRF3 protects male mice against high-fat diet-induced insulin resistance, whereas overexpression of IRF3 or AIG1 in adipocytes promotes insulin resistance on a high-fat diet." (PMID 38816388, 2024). "We, therefore, identify the adipocyte IRF3/AIG1 axis as a crucial link between obesity-induced inflammation and insulin resistance and suggest an approach for limiting the metabolic dysfunction accompanying obesity." (PMID 38816388, 2024). "Furthermore, pharmacological inhibition of AIG1 reversed obesity-induced insulin resistance and restored glucose homeostasis in the setting of adipocyte IRF3 overexpression." (PMID 38816388, 2024). "In addition, a novel small molecule inhibitor of AIG1 raises FAHFA levels and attenuates HFD-induced insulin resistance and glucose intolerance in FI3OE mice." (PMID 38816388, 2024). "Interestingly, targeted ablation of AIG1 in all tissues failed to protect mice from HFD-induced insulin resistance and glucose intolerance." (PMID 38816388, 2024).
iron deficiency (1 paper, 2014). "Three AIG1 transcripts (EHI_115160, EHI_022500, and EHI_195260) were upregulated in iron deficiency." (PMID 25210888, 2014).
Liver abscess (1 paper, 2023). A circumscribed area of pus or necrotic debris in the liver. "Similarly, differential expression was detected during E. histolytica invasion of the mouse intestine, and aig1 genes were downregulated in trophozoites isolated from an amoebic liver abscess." (PMID 38134215, 2023).
pancreatic cancer (1 paper, 2024). "Similarly, in pancreatic cancer coculture, most of the genetic material was non-annotated followed by AIG1, MCF2L2 and PRIM2 among others." (PMID 38783375, 2024).
prostate carcinoma (1 paper, 2017). A carcinoma that arises from epithelial cells of the prostate gland. "The prostate transmembrane protein, androgen induced 1 (PMEPA1), is another important target gene of TGF-β signaling and highly expressed in many types of cancers including colon, breast, lung and prostate cancer, whereas reports about the expression of PMEPA1 in HCC patients are lacking." (PMID 28230858, 2017).
T cell lymphoma (1 paper, 2021). "Other studies also indicated that AIG1 is involved in cancer-related processes; e.g., AIG1 can form complexes with either nuclear factor 1/B in salivary adenoid cystic carcinoma or Golgi SNAR complex member 1 in T cell lymphoma." (PMID 34440364, 2021).
infection (8 papers, 2010 to 2024). The state of being infected such as from the introduction of a foreign agent such as serum, vaccine, antigenic substance or organism. "The gene, encoding AIG1, which is a GTPase domain-containing protein, was originally identified as being upregulated in a strain of Pseudomonas syringae pv maculicola following infection of Arabidopsis thaliana; this gene may, therefore, be involved in immune responses in plants." (PMID 29554130, 2018). "AIG1, which is induced by infection by bacteria carrying the avirulence gene avrRpt2, likely elicits differential resistance responses based on the type of avirulence gene and its recognition partner." (PMID 29052098, 2017). "Trophozoites isolated from the cecal lumen of mice early in infection (day 1) showed either an unregulated or an increased expression of aig1 genes." (PMID 20102605, 2010). "Although L. martiniquensis strains Mar1, Cu1R1, and Aig1 did not cause any pathological signs of infection, animals infected with L. martiniquensis Cu2 showed the most severe cutaneous signs of infection of all tested groups." (PMID 38739677, 2024). "Immediately following pathogen infection, avrRpt2 and RPS2 induce AIG1 (avrRpt2 induced gene 1), which may cause cell death." (PMID 37821523, 2023). "Interestingly, in addition to the induction of AIG1 in Arabidopsis by infection, in both coral and molluscs AIG1 family members are also induced by pathogenic challenge, suggesting that they may have a significant role in conferring resistance to infection." (PMID 29718959, 2018).
cancer (6 papers, 2016 to 2025). A tumor composed of atypical neoplastic, often pleomorphic cells that invade other tissues. "Previous studies on AIGs demonstrated that one member of the gene family, AIG1, is involved in many biological processes in cancer cell lines and that ADTRP is associated with cardiovascular diseases." (PMID 34440364, 2021). "More studies are warranted to further confirm the benefits of AIG1 in DIC among cancer patients and to uncover its broader roles in cancer contexts." (PMID 40303337, 2025). "The upregulated lnc-PMEPA1-2:1 is a 361 bp sense-overlapping lncRNA and was predicted to have a cis target gene, prostate transmembrane protein, androgen-induced 1(PMEPA1), which is important in cancer development." (PMID 28511643, 2017).
bacterial infection (2 papers, 2010 to 2023). "The first family member, AIG1, was discovered in Arabidopsis thaliana, and its expression was induced in defense against bacterial infection or abiotic stressors." (PMID 36986411, 2023). "It is suggested that the plant homolog AIG1 is involved in cell death regulation following self-defence responses to bacterial infection." (PMID 20102605, 2010).
cardiovascular diseases (2 papers, 2021 to 2025). "This discovery proposes a novel perspective on the pathogenesis and potential therapeutic strategies for DIC, and also provides valuable insights for future research into the role of AIG1 in other cardiovascular diseases." (PMID 40303337, 2025).
tumor (2 papers, 2016 to 2025). "Last but not least, the effects of AIG1 were not assessed in a tumor-bearing mouse model of DIC and AIG1 expression levels were unable to be validated in human heart samples of DIC due to apparent difficulties to access human samples." (PMID 40303337, 2025).
AIG1 also shares sentences with these, for which no sentence is quoted: cyst (1 paper); Hernia (1); movement disorder (1); nematode infection (1); neurological disorders (1); neuromuscular disease (1); Obesity (1); Parkinson disease (1).